ANLN (anillin, actin binding protein)
Diseases named in the same sentence as ANLN in open-access papers (continued):
Sharing a sentence is not in itself a finding about the gene and the disease.
pancreatic cancer (continued). "In summary, we have identified the ANLN/EZH2/miR-218-5p/LASP1 signaling axis in pancreatic cancer cells, which provides new insights into the mechanism underlying pancreatic cancer progression and generates a mechanism-based novel framework for developing therapeutics in pancreatic cancer treatment." (PMID 31395079, 2019). "Taken together, ANLN may promote pancreatic cancer cell growth, migration and invasion by regulating EZH2/miR-218-5p/LASP1 signaling axis." (PMID 31395079, 2019). "Moreover, LASP1 re-expression partially reversed the effect of ANLN knockdown on pancreatic cancer cell migration and invasion." (PMID 31395079, 2019). "Other studies have found that ANLN could promote the progression of pancreatic cancer by inducing the up-regulation of EZH2 by mediating the mir-218-5p /LASP1 signaling axis." (PMID 31681575, 2019). "Taken together, EZH2 induced by ANLN may promote pancreatic cancer progression by regulating miR-218-5p/LASP1 signaling axis." (PMID 31395079, 2019). "Thus, it is necessary to study the roles of miR-218-5p in ANLN-induced pancreatic cancer progression." (PMID 31395079, 2019). "Moreover, ANLN was upregulated in pancreatic cancer and was involved in miR-217-mediated cell proliferation and invasion." (PMID 31395079, 2019). "In addition, the CCK-8 and colony formation assays indicated that the suppressive effects of ANLN knockdown on pancreatic cancer cell growth were restored by LASP1 re-expression." (PMID 31395079, 2019). "Whether LASP1 is involved in ANLN-induced pancreatic cancer progression is what we deal with in this study." (PMID 31395079, 2019). "In addition, ANLN also has specific regulatory effects in pancreatic cancer." (PMID 41573677, 2025). "In addition, EZH2/miR-218-5p/LASP1 signaling axis might be involved in ANLN-mediated cell proliferation, colony formation, migration and invasion in pancreatic cancer." (PMID 31395079, 2019). "Moreover, ANLN could serve as an independent predictor for overall survival of pancreatic cancer patients." (PMID 31395079, 2019). "Therefore, ANLN may promote pancreatic cancer cell progression and miR-218-5p/LASP1 signaling axis by mediating EZH2." (PMID 31395079, 2019). "Thus, cell-cell adhesion-related genes with altered expression in BxPC-3 cells after ANLN knockdown may play an important role in ANLN-induced pancreatic cancer cell progression." (PMID 31395079, 2019). "Thus, we hypothesized that ANLN may induce the silencing of miR-218-5p by mediating EZH2 in pancreatic cancer progression." (PMID 31395079, 2019). "Many recent studies suggests that ANLN is upregulated in numerous cancer types, including cervical cancer, prostate cancer, anaplastic thyroid carcinoma, breast cancer, lung carcinogenesis, bladder urothelial carcinoma, pancreatic cancer and nasopharyngeal carcinoma." (PMID 31395079, 2019). "Thus, ANLN may be a useful prognostic indicator and an important therapeutic target in the treatment of pancreatic cancer." (PMID 31395079, 2019). "Furthermore, ANLN was identified as a prognostic biomarker and an increase in ANLN mRNA from normal tissue to malignant disease was observed in breast, lung, bladder, gastric, colorectal, nasopharyngeal and pancreatic cancer." (PMID 30103211, 2018). "Our integrative single-cell and bulk-RNA workflow identifies ANLN, NT5E, and CTSV as novel prognostic biomarkers in pancreatic cancer and highlights a pro-tumorigenic interaction between malignant ductal cells and macrophages." (PMID 40666516, 2025). "In pancreatic cancer, PUS7 promotes malignant phenotypes through its interaction with anillin (ANLN), thereby activating the MYC signaling pathway." (PMID 40940790, 2025). "Here, we screened key DEGs in pancreatic cancer, searched the upstream miRNAs and lncRNAs based on key DEGs, and finally constructed a MIR600HG/hsa-miR-342-3p/ANLN network." (PMID 37741887, 2023).
pancreatic cancer (continued). "The expression of ANLN protein was predominately localized in the nucleus in GC and CRC and in the cytoplasm and membrane in HCC and pancreatic cancer." (PMID 35568883, 2022). "In comparison with corresponding normal tissues, ANLN was upregulated in HCC, GC, CRC, and pancreatic cancer tissues." (PMID 35568883, 2022). "Five mRNAs were shared between the two datasets, with SLC3A1 and IAPP down-regulated whereas CXCL14, ANLN, and TPRS1 up-regulated in pancreatic cancer." (PMID 33925948, 2021). "Then, we screened ANLN and MYEOV related to prognosis and the immune microenvironment in pancreatic cancer." (PMID 34394706, 2021). "ANLN and MYEOV are involved in the progress of pancreatic cancer and are expected to become new markers and therapeutic targets in the future." (PMID 34394706, 2021). "However, the precise role of ANLN in pancreatic cancer remains unclear." (PMID 31395079, 2019). "Thus, ANLN may promote pancreatic cancer cell progression by regulating LASP1." (PMID 31395079, 2019). "Interestingly, most of the relationships between drug resistance and the expression levels of the up-UDEGs ANLN, GPRC5A and SERPINB5 were positive, indicating that these three genes are closely related to the resistance mechanisms of pancreatic cancer." (PMID 40362181, 2025). "Similarly, for ANLN and MYEOV, we need more external data and experiments to prove that they are related to the prognosis and immune microenvironment of pancreatic cancer." (PMID 34394706, 2021). "The low expression of miR-217 in pancreatic cancer patients was confirmed in two gene expression datasets (GSE41372 and GSE60980), and the prognostic value of two target genes (ANLN and TRPS1), was estimated on clinical data from the Tumor Cancer Genome Atlas (TCGA)." (PMID 33925948, 2021). "Correlation analysis between ANLN and MYEOV and immunomodulators showed that ANLN and MYEOV may have potential value in pancreatic cancer immunotherapy." (PMID 34394706, 2021). "(C) CCK-8 assay showed that LASP1 restoration partially reversed the effects of ANLN knockdown on pancreatic cancer cell proliferation, while RUVBL1 restoration did not reverse the effect of ANLN downregulation on pancreatic cancer cell proliferation." (PMID 31395079, 2019). "Moreover, we analyzed the ANLN protein expression in one normal human pancreatic duct epithelial cell line (hTERT-HPNE) and five pancreatic cancer cell lines (AsPC-1, PANC-1, BxPC-3, MIA PaCa-2 and SW1990)." (PMID 31395079, 2019). "However, RUVBL1 restoration did not reverse the effect of ANLN downregulation on pancreatic cancer cell proliferation." (PMID 31395079, 2019). "However, the relationship between EZH2/miR-218 axis and ANLN in pancreatic cancer progression has not been studied before." (PMID 31395079, 2019). "Thus, ANLN may regulate LASP1 expression and pancreatic cancer progression by miR-218-5p." (PMID 31395079, 2019).
lung adenocarcinoma (25 papers, 2019 to 2026). A carcinoma that arises from the lung and is characterized by the presence of malignant glandular epithelial cells. "The Cancer Genome Atlas data analysis revealed 27 mutations in 446 patients with lung adenocarcinoma, with five mutations affecting the conserved amino acids of ANLN." (PMID 32560530, 2020). "lncRNA CERS6-AS1 promotes lung adenocarcinoma progression and drug resistance by upregulating ANLN expression through sponge miR-424-5p." (PMID 40264452, 2025). "ANLN is an actin-binding protein, and related studies have confirmed that ANLN can affect lung adenocarcinoma progression by promoting epithelial mesenchymalization." (PMID 38243040, 2024). "Zhang and collaborators (2021) have identified seven N6-methyladenosine-related immune prognostic genes (i.e., PSMD10P1, DIDO1, ABCA5, CIITA, PRC1, ZWILCH, and ANLN) for lung adenocarcinoma (LUAD)." (PMID 37189849, 2023). "For example, overexpression of ANLN promoted cell metastasis in lung adenocarcinoma, and patients with higher ANLN expression displayed much worse prognosis." (PMID 34082790, 2021). "In other research, there is evidence showing that ANLN is also related to metastasis in lung adenocarcinoma (A549, PC9)." (PMID 32560530, 2020). "Furthermore, there is also evidence showing that ANLN expression correlates with lung adenocarcinoma metastasis." (PMID 37007961, 2023). "Another study revealed that ANLN might be involved in the metastasis of lung adenocarcinoma by promoting epithelial mesenchymal transformation of tumor cells." (PMID 36030492, 2023). "In lung adenocarcinoma, ANLN is identified as a potential prognostic marker and may affect the epithelial-mesenchymal transition process." (PMID 36199577, 2022). "ANLN may be involved in the metastasis of lung adenocarcinoma by promoting the epithelial mesenchymal transformation of tumour cells." (PMID 32560530, 2020). "Furthermore, ANLN was identified as a biomarker for the prognosis of bladder urothelial carcinoma, colorectal cancer, and lung adenocarcinoma." (PMID 31392101, 2019). "Knockdown assays using siRNAs revealed that ANLN and MAD2L1 facilitated the malignant transformation of lung adenocarcinoma cells." (PMID 40723231, 2025). "Like ANLN, TOP2A positively regulates invasion and migration and promotes EMT in lung adenocarcinoma, and in PC, TOP2A expression gives rise to enhanced cell proliferation, migration, and EMT." (PMID 34591244, 2021). "Based on GEPIA database, seven of the top ten co-expressed genes were highly expressed in lung adenocarcinoma (DSC2, SLC2A1, ARNTL2, ERO1L, ECT2, ANLN and LAMC2)." (PMID 32095325, 2020). "Finally, seven copper death genes related to lung adenocarcinoma were screened out, including ARHGEF39, EFCC1, SERPIND1, INSL4, ANLN, RHOV and CCL20." (PMID 36313444, 2022).
colorectal cancer (20 papers, 2018 to 2025). A primary or metastatic malignant neoplasm that affects the colon or rectum. "Based on the analysis of colorectal cancer tissues, ANLN is supposed to be associated with colorectal cancer development and with a poor prognosis." (PMID 32560530, 2020). "ANLN is highly expressed in colorectal cancer(CRC) tissues, and its expression is positively correlated with tumor invasion and growth." (PMID 41573677, 2025). "In colorectal cancer, six genes were positively correlated: ANLN, ACOT7, OSBPL3, SEC61G, DDX56, and TRIM10." (PMID 40765570, 2025). "In gastrointestinal cancers—including hepatocellular carcinoma, gastric cancer, and colorectal cancer-ANLN mRNA levels are elevated compared to normal cell lines." (PMID 41332473, 2025). "Further, regarding the relevance of ANLN in oncologic chemotherapy, in patients with breast and colorectal cancers, ANLN expression was negatively correlated with sensitivity to chemotherapeutic drugs." (PMID 35991576, 2022). "Dysregulation of ANLN expression has already occurred in various human cancers such as breast and colorectal cancers." (PMID 35373928, 2022). "Patients with breast and colorectal cancer who presented high ANLN expression showed resistance to chemotherapy." (PMID 35991576, 2022). "Reverse transcription quantitative polymerase chain reaction and immunohistochemistry were used to determine ANLN mRNA and protein expression in colorectal cancer (CRC), gastric cancer (GC), and hepatocellular carcinoma (HCC) cell lines." (PMID 35568883, 2022). "Similarly, AURKA, BAG3, NUBP1, and ANLN are all found to be dysregulated in colorectal cancer and involved in cancer progression and invasion." (PMID 34790220, 2021). "Overexpression of ANLN was correlated with colorectal cancer progression." (PMID 33193642, 2020).
hepatocellular carcinoma (20 papers, 2018 to 2026). A malignant tumor that arises from hepatocytes. "Editor's choice:Comparison between five N-acetylgalactosamine-conjugated siRNAs in several mouse models of liver cancer found ANLN to be a promising target for hepatocellular carcinoma chemoprevention." (PMID 40704506, 2025). "While ANLN has emerged as a potential biomarker for hepatocellular carcinoma, its precise role in cancer treatment remains an area for further exploration." (PMID 41573677, 2025). "A large number of studies showed that the overexpression of ANLN was detected in various types of cancers, e.g., pancreatic ductal adenocarcinoma, colon, lung, gastric, and hepatocellular carcinoma." (PMID 39728605, 2024). "ANLN is associated with the progression of lung, pancreatic, and cervical cancers, whereas UBE2T is associated with proliferation in hepatocellular carcinoma, glioblastoma, gastric cancer, and renal cell carcinoma." (PMID 35578283, 2022). "In the context of HBV-induced hepatocellular carcinoma, we found ANLN (anillin actin-binding protein) as a DDX5-specific interactor." (PMID 35954483, 2022). "Particularly, in hepatocellular carcinoma, the ANLN transcriptional level was at a fold change of 16.3 in tumor vs normal tissue." (PMID 30103211, 2018). "In summary, we found that HSG (PTTG1, ANLN, KIF2C, TPX2) was significantly upregulated in hepatocellular carcinoma and that the constructed prognostic risk model can reliably predict the prognosis of hepatocellular carcinoma patients." (PMID 38887516, 2024). "ANLN was recorded to be involved in apoptosis in hepatocellular carcinoma (HCC)." (PMID 32560530, 2020). "Overexpression of ANLN is related to poor prognosis in patients with hepatocellular carcinoma." (PMID 33261584, 2020). "In agreement with previous studies, USP10 acts as an oncoprotein in hepatocellular carcinoma, esophageal squamous cell carcinoma, glioblastoma, and acute myeloid leukemia through the stabilization of YAP, ANLN, RUNX1, and FLT3." (PMID 40605431, 2025). "Startlingly, nuclear ANLN has been shown to form a transcriptional complex with SP1, thus enhancing KIF2C transcriptional activity and activating the mTORC1 pathway, which leads to the hepatocellular carcinoma bone metastasis." (PMID 41513610, 2026). "ANLN expression is significantly upregulated in hepatocellular carcinoma(HCC) tissues compared to adjacent non-tumor tissues." (PMID 41573677, 2025).
bladder cancer (13 papers, 2017 to 2025). "We found that high ANLN expression was associated with the clinical benefits of ICB therapy (PD-1) in patients with bladder cancer and glioblastoma, while low ANLN expression was associated with the clinical benefits of ICB therapy (PD-L1 or PD-1) in patients with kidney cancer and melanoma." (PMID 35991576, 2022). "Comparison between bladder cancer tissues and paracancerous tissues according to the expression levels of ANLN and ASPM genes in total samples (N = 35), NMIBC (N = 26) and MIBC (N = 9)." (PMID 37051591, 2023). "In patients with bladder cancer and melanoma, high ANLN expression was positively correlated with CTL levels." (PMID 35991576, 2022). "In this study, our results showed that alterations in ANLN were most common in uterine cancer, followed by bladder cancer, UCEC, and SKCM." (PMID 35568883, 2022). "Functional studies further demonstrated that ANLN participated in the regulation of bladder cancer cell proliferation, migration and invasion, along with the cell cycle." (PMID 28600503, 2017). "Meanwhile CCNB1, CENPF and BUB1B genes were revealed to be positively co-expressed with ANLN in bladder cancer from three different datasets." (PMID 28600503, 2017). "Similarly, studies in bladder cancer show that ANLN knockdown triggers G2/M arrest and decreases Cyclin B1 and Cyclin D1 expression, thereby suppressing tumor growth." (PMID 41573677, 2025). "Indeed, published works by others have reported expressional dysregulation of many signaling pathways after depletion of ANLN expression in breast, pancreatic, and bladder cancer cell lines." (PMID 35340220, 2022). "Additionally, high ANLN expression was associated with clinical benefits derived from ICB therapy (PD-1), and thus longer OS, in patients with bladder cancer and glioblastoma." (PMID 35991576, 2022). "In bladder cancer, there was ANLN overexpression, which could promote tumor cell proliferation, migration, and infiltration; moreover, this was confirmed in vitro experiments." (PMID 35991576, 2022). "Furthermore, knockdown of ANLN strongly suppressed the migration and invasion ability of J82 and 5637 bladder cancer cell lines." (PMID 31766561, 2019). "Previous research has established that knockdown of ANLN could significantly inhibit the proliferation of bladder cancer both in vitro and in vivo." (PMID 31766561, 2019). "In conclusion, we identified ANLN through RNA-seq as a frequently overexpressed gene in bladder cancer, and proved that ANLN could serve as a single and highly predictive prognostic biomarker in BLCA by using both internal and public cohort validation." (PMID 28600503, 2017). "In addition, we revealed that ANLN played a crucial role in the carcinogenesis of bladder cancer by participating in the regulation of proliferation, migration, invasion and cell cycle progression in BLCA cells." (PMID 28600503, 2017). "CDCA3, ANLN, STMN1, and DHCR24 play important roles in cell proliferation and migration of bladder cancer." (PMID 39540204, 2024). "Relationship of the expression levels of ANLN and ASPM genes with clinicopathological characteristics in bladder cancer." (PMID 37051591, 2023). "ANLN and TLE2 are promising biomarkers for individualized bladder cancer therapy including cancer subclassification and informed MIBC prognosis." (PMID 31766561, 2019). "In our study, expression of ANLN and TLE2 correlate with the therapeutic targets for bladder cancer as indicated in existing research and clinical trials." (PMID 31766561, 2019). "Moreover, ANLN can upregulate the expression of MAPK8/MAPK9, activate phosphorylated JNK, and enhance the proliferation, migration, and invasion of bladder cancer cells while inhibiting apoptosis." (PMID 41573677, 2025).
cervical cancer (12 papers, 2019 to 2025). A primary or metastatic malignant neoplasm involving the cervix. "Analysis of the GEO database and clinical samples has demonstrated that ANLN is highly expressed in cervical cancer." (PMID 41573677, 2025). "In cervical cancer, ANLN activates EZH2 to drive EMT and inhibit apoptosis, thereby enhancing tumor cell migration." (PMID 41573677, 2025). "ANLN is involved in cell division and is upregulated in various cancers such as pancreatic and cervical cancer." (PMID 37374977, 2023). "Some other studies have shown DSG2, PLOD2, ANLN, AURKA, and AR genes might be key genes associated with cervical cancer progression." (PMID 41266827, 2025). "Furthermore, meta-analysis results confirmed that ANLN was overexpressed in cervical cancer, HNSC, CRC, BLCA, and STAD in the Oncomine database (P < 0.05)." (PMID 35568883, 2022). "Some researchers found that ANLN is a key candidate gene for cervical cancer and HBV-related HCC." (PMID 32903581, 2020). "Furthermore, bioinformatics analysis has suggested that ANLN may form a cell cycle regulatory network with CCNE2/CDK1/AURKA, which is associated with lymph node metastasis in cervical cancer." (PMID 41573677, 2025). "Downregulation of ANLN and ECT2 led to predicted repression of cytokinesis of cervical cancer cell lines (p < 0.05)." (PMID 38785827, 2024).
gastric cancer (11 papers, 2007 to 2025). A primary or metastatic malignant neoplasm involving the stomach. "In gastric cancer, ANLN can promote cell proliferation by activating the Wnt/β-catenin signaling pathway." (PMID 35991576, 2022). "ANLN overexpression correlated with worse outcomes in a wide spectrum of malignancies including lung, breast, and gastric cancer." (PMID 35444699, 2022). "A previous study showed that ANLN expression in gastric cancer (GC) is a molecular predictor of intestinal and proliferative type gastric tumors." (PMID 31392101, 2019). "In addition, ANLN expression is also positively related to Wnt/β‐catenin signaling in gastric cancer." (PMID 36030492, 2023). "Besides, ANLN could be confirmed to be a Wnt/β-catenin responsive gene in gastric cancer, and it can regulate the proliferation of gastric cancer cells." (PMID 32560530, 2020).